TRIM23 (tripartite motif containing 23)
Description:
E3 ubiquitin ligase that harbors GTPase activity encoded by the C-terminal ARF domain. Plays an essential role in autophagy activation during viral infection. Mechanistically, activates TANK-binding kinase 1/TBK1 by facilitating its dimerization and ability to phosphorylate the selective autophagy receptor SQSTM1. In order to achieve this function, TRIM23 mediates 'Lys-27'-linked auto-ubiquitination of its ADP-ribosylation factor (ARF) domain to induce its GTPase activity and its recruitment to autophagosomes. Catalyzes 'Lys-63'-linked polyubiquitination of HAX1 that triggers its liquid-liquid phase separation (LLPS) and contributes to P-bodies assembly induced by energy stress. (Microbial infection) Mediates TRAF6 auto-ubiquitination in the presence of human cytomegalovirus protein UL144, resulting in the virally controlled activation of NF-kappa-B stimulation at early times of HCMV infection.
Synonyms: ARD1; ARFD1; RNF46
Tractability: Antibody: its Gene Ontology location is reachable by antibodies, with medium confidence. PROTAC: ubiquitination databases record sites on it.
Gene: Protein-coding gene on chromosome 5 (65,589,690 to 65,625,975, reverse strand). Ensembl gene ENSG00000113595.
Subcellular location: Cytoplasm; Endomembrane system; Golgi apparatus membrane; Lysosome membrane; Cytoplasm, P-body
Gene Ontology:
Molecular function: GDP binding; GTP binding; GTPase activity; identical protein binding; protein binding; ubiquitin protein ligase activity; ubiquitin-protein transferase activity; enzyme activator activity; zinc ion binding
Biological process: positive regulation of autophagy; protein ubiquitination; intracellular protein transport
Cellular component: cytoplasm; Golgi membrane; lysosomal membrane; plasma membrane; endomembrane system; nucleus; P-body
Genetic constraint (gnomAD): Loss-of-function variants: 25 observed, 66.64 expected, observed/expected ratio (o/e) 0.38, 90% interval 0.27 to 0.52. The upper end of that interval is the gene's LOEUF score, 0.52, which puts it in group 2 of 6, group 1 being the genes least tolerant of losing a copy. Missense variants: 463 observed, 684.21 expected, observed/expected ratio (o/e) 0.68, 90% interval 0.63 to 0.73. Synonymous variants: 225 observed, 235.52 expected, observed/expected ratio (o/e) 0.96, 90% interval 0.86 to 1.07.
Homologues: Orthologues: chimpanzee TRIM23 (100% identical), macaque TRIM23 (100% identical), mouse Trim23 (98% identical), rat Trim23 (98% identical), pig TRIM23 (98% identical), dog TRIM23 (97% identical), rabbit TRIM23 (97% identical), guinea pig TRIM23 (97% identical), tropical clawed frog trim23 (88% identical), zebrafish trim23 (88% identical), Caenorhabditis elegans arc-1 (35% identical). Paralogues in human: ARF1 (19% identical), ARF3 (19% identical), ARF4 (18% identical), ARF5 (18% identical), ARF6 (17% identical), ARL1 (16% identical), ARL2 (14% identical), ARL3 (14% identical), ARL5A (14% identical), ARL4C (13% identical), ARL4A (13% identical), ARL14 (13% identical), and 18 more.
Diseases named in the same sentence as TRIM23 in open-access papers:
TRIM23 is named in the same sentence as 11 diseases in open-access papers, as found by Europe PMC text mining. Sharing a sentence is not in itself a finding about the gene and the disease. The quoted sentences say what the papers report.
colorectal cancer (7 papers, 2020 to 2025). A primary or metastatic malignant neoplasm that affects the colon or rectum. "Another decreased protein was the tripartite motif containing 23 (TRIM23), which contributes to carcinogenesis in colorectal cancer and act as a poor prognostic factor." (PMID 39833546, 2025). "For instance, increased TRIM23 expression is correlated with a poor prognosis in colorectal cancer and lung adenocarcinoma." (PMID 34065345, 2021). "Our study provides experimental evidence that TRIM23 is overexpressed significantly in colorectal cancer, and the immunostaining intensity of TRIM23 correlates positively with lymph node metastasis, tumour size and AJCC stage." (PMID 32227572, 2020). "TRIM23 expression was significantly increased in colorectal cancer tissues compared with normal adjacent tissues." (PMID 32227572, 2020). "High‐throughput RNA‐sequencing data set of the colorectal cancer cohort from GEO and the data set from TCGA were used to perform GSEA to probe the TRIM23‐associated signal pathways in an unbiased manner." (PMID 32227572, 2020). "In summary, our study has shown the clinical and biological significance of TRIM23 in colorectal cancer." (PMID 32227572, 2020). "However, the expression pattern, prognostic value and biological functions of tripartite motif containing 23 (TRIM23) in colorectal cancer (CRC) are poorly understood." (PMID 32227572, 2020). "The data strongly suggested that TRIM23 may promote colorectal cancer progression by regulating colorectal cancer cell proliferation." (PMID 32227572, 2020). "Additionally, multiple microarray data sets of colorectal cancer from TCGA were analysed, and we found that the TRIM23 expression level was significantly higher in tumour tissues than in normal adjacent tissues." (PMID 32227572, 2020). "The exact signalling pathway that TRIM23 may regulate in colorectal cancer remains unclear." (PMID 32227572, 2020). "For example, in colorectal cancer, SNHG17 competes with the E3 ligase Trim23 to bind Pescadillo (PES1), protecting PES1 from degradation." (PMID 36185210, 2022). "In colorectal cancer, SNHG17 lncRNA inhibited PES1 ubiquitination and degradation via blocking the interaction of Trim23 and PES1." (PMID 35977942, 2022). "Furthermore, high HAX1 ubiquitination, and increased cytoplasmic localization of TRIM23 along with elevated HAX1 levels, promotes colorectal cancer (CRC)-cell proliferation and correlates with poor prognosis in CRC patients." (PMID 38769438, 2024).
viral infection (5 papers, 2022 to 2025). "Viral infection promotes TRIM23 autoubiquitination through K27-linked polyubiquitin on its ARF domain which activates an additional TRIM23 GTPase function." (PMID 40285004, 2025). "A study reported that TRIM23 promotes the dimerization of TBK1 during viral infection, which in turn facilitates the phosphorylation of serine at site 403 of p62 to initiate autophagy." (PMID 40234418, 2025). "A study reported that TRIM23 promotes TBK1 dimerization during viral infection and mediates autophagy through the TBK1-p62 axis." (PMID 40234418, 2025). "RNAi screening of TRIM proteins identified TRIM23 as essential for autophagy in response to viral infection." (PMID 40285004, 2025). "Our results will provide new insights into understanding the mechanism of fish TRIM23 against viral infection." (PMID 36203610, 2022). "Although great efforts have been made on the roles of mammalian TRIM23 in response to virus infection, few reports focused on the function of TRIM23 from lower vertebrates, especially from fish." (PMID 36203610, 2022). "Whether grouper TRIM23 was involved in different fish viruses infection, and the potential mechanism still remained uncertain." (PMID 36203610, 2022). "Among them, TRIM23 acts as an important regulatory factor in antiviral immune and inflammatory responses, but the roles of fish TRIM23 against virus infection still remain largely unknown." (PMID 36203610, 2022). "Thus, we speculated that fish TRIM23 exhibited different expression profiles against different viruses infection." (PMID 36203610, 2022). "TRIM23 promotes p62 (a.k.a., sequestosome 1, SQSTM1)-mediated selective autophagy during viral infection via the TRIM23-TBK1-p62 axis." (PMID 39861861, 2025).
lung adenocarcinoma (2 papers, 2021 to 2024). A carcinoma that arises from the lung and is characterized by the presence of malignant glandular epithelial cells. "In lung adenocarcinoma, TRIM23 expression was shown to correlate with resistance to the chemotherapeutic agent cisplatin which was suggested to be the result of induced GLUT1/3 expression and inhibition of NF-κβ." (PMID 34065345, 2021). "Some literatures have shown that TRIM23, a member of the E3 ubiquitin ligase TRIM family, acts as an oncogene in lung adenocarcinoma (LUAD) and regulates glucose metabolism through the TRIM23/NF- κ B/GLUT1/3 axis to promote DDP drug resistance." (PMID 39389957, 2024).
bipolar disorder (1 paper, 2007). A disorder of the brain that causes unusual shifts in mood, energy, activity levels and the ability to carry out day-to-day tasks. "Among this study's suicide candidate genes associated with bipolar disorder, the tripartite motif-containing 23 (TRIM23) gene is located close to the significantly linked D5S1725 marker on chromosome 5." (PMID 17997842, 2007).
cytomegalovirus infection (1 paper, 2014). A herpesvirus infection caused by Cytomegalovirus. "TRIM23 acts as a cofactor in the regulation of NF-ҡB activation in human cytomegalovirus infection." (PMID 24485101, 2014).
diabetes mellitus (1 paper, 2015). A metabolic disorder characterized by abnormally high blood sugar levels due to diminished production of insulin or insulin resistance/desensitization. "Results of further studies on TRIM23 may be useful for revealing the abnormalities in adipocyte differentiation and for providing a potential therapeutic target for obesity and diabetes mellitus." (PMID 25905670, 2015). "By providing new insights into how adipogenesis is regulated, these findings suggest that TRIM23 may be a potential therapeutic target in the treatment of diabetes and disorders related to obesity." (PMID 25905670, 2015).
lymph node metastasis (1 paper, 2020). "TRIM23 expression was notably associated with tumour size (P = .031), lymph node metastasis (P = .016) and AJCC stage (P = .027)." (PMID 32227572, 2020).
tumor (6 papers, 2019 to 2025). "Here, we found that TRIM23 is up‐regulated and associated with tumour size, lymph node metastasis, American Joint Committee on Cancer (AJCC) stage and poor prognosis in CRC." (PMID 32227572, 2020). "Our data showed that TRIM23 mRNA levels were notably increased in tumour tissues compared with that in normal tissues." (PMID 32227572, 2020). "The ability to track the genomic evolution from primary to metastatic MPNST offers new insights into the sequence of genetic events required for tumor progression and has identified TRIM23 as a novel target for future study in this rare cancer." (PMID 32642734, 2020). "We found that TRIM23 knock‐down obviously inhibited tumour growth rate in mice (P < .01)." (PMID 32227572, 2020). "The weight of TRIM23‐knock‐down tumours was less than that of control tumours." (PMID 32227572, 2020). "Mechanistically, SNHG17 interacts with PES1 to inhibit the Trim23-mediated ubiquitination of PES1, resulting in increased PES1 stability and enhanced tumor growth and metastasis." (PMID 34782005, 2021). "Similar to TRIM23, the overexpression of TRIM24 which is synonymously known as transcription intermediary factor 1α (TIF1α), positively correlates with tumor size and shorter survival time of CRC patients as indicated by Kaplan–Meier survival analysis." (PMID 33066016, 2020). "Tumour cells in the galectin-1-rich environments express genes important for tumour progression such as SPIN1, FUSIP1, TRIM23, PTPLAD1, MAP3K2." (PMID 30925774, 2019).
cancer (5 papers, 2019 to 2024). A tumor composed of atypical neoplastic, often pleomorphic cells that invade other tissues. "In addition, TRIM58 or TRIM23 exhibited lower expression in multiple cancer types." (PMID 36461099, 2022). "On the contrary, TRIM23, TRIM61 and TRIM58 have lower expression in cancer." (PMID 36461099, 2022).
infection (5 papers, 2015 to 2025). The state of being infected such as from the introduction of a foreign agent such as serum, vaccine, antigenic substance or organism. "TRIM23‐siRNA infection caused a obvious increase of G0/G1‐phase cells and a decrease of S and G2/M‐phase cells compared with the non‐specific scramble siRNA group." (PMID 32227572, 2020). "This is an interesting observation as LPAI virus can replicate in ducks for many days past initial infection, and the upregulation of TRIM23 suggests it is worth investigating whether it affects viral replication." (PMID 32477965, 2020). "TRIM23 was identified as a differentially expressed gene in a microarray study from ducks infected with both HPAI and LPAI strains of IAV, as upregulated 5 DPI in LPAI but not HPAI infections." (PMID 32477965, 2020).
TRIM23 also shares sentences with these, for which no sentence is quoted: Obesity (1 paper).